PIEZO1 (piezo type mechanosensitive ion channel component 1 (Er blood group))
Diseases named in the same sentence as PIEZO1 in open-access papers (continued):
Sharing a sentence is not in itself a finding about the gene and the disease.
malaria (12 papers, 2022 to 2025). Malaria is a serious and sometimes fatal disease caused by a parasite that commonly infects a certain type of mosquito which feeds on humans. "The protective mechanism of the Er blood group system against malaria operates through precisely regulated biomechanical and biochemical pathways mediated by PIEZO1 gain-of-function mutations." (PMID 41450567, 2025). "E756del has been associated with malaria resistance, which is suggested to constitute a selective advantage within regions of high malaria prevalence, resulting in PIEZO1 GOF being present in one-third of the African population." (PMID 37227181, 2023). "Secondarily, RBC dehydration (that is delayed in the standard RPMI/albumax parasite culture medium) further contributes to enhance protection against malaria, as previously observed for the PIEZO1 E756del GOF variant." (PMID 37071200, 2023). "The mechanisms implicated in the protection conferred by the PIEZO1 E756del against severe malaria appear to be complex and remain disputed." (PMID 37071200, 2023). "A common PIEZO1 polymorphism was recently found associated with protection from severe malaria in humans, a clear target for a study on the possible mechanism of protection using the model of falciparum-infected RBCs." (PMID 36588342, 2023). "Altogether, our in vitro findings further support a role for PIEZO1 in the host RBC contributing to the resistance against severe malaria in vivo conferred by a GOF mutation in PIEZO1." (PMID 37071200, 2023). "Along this line, another GOF PIEZO1 variant (E756del), present in about 1/3 of the black population from Western Africa, also confers a significant resistance against severe malaria." (PMID 37071200, 2023). "An inherited gain-of-function variant (E756del) in the mechanosensitive cationic channel PIEZO1 was shown to confer a significant protection against severe malaria." (PMID 37071200, 2023). "Recently, a common genetic variant E756del in the human gene PIEZO1 was associated with protection from severe malaria." (PMID 34230590, 2022). "The statistical analysis did not indicate an association with protection from severe malaria and, thus, providing evidence against a strong protective effect of the PIEZO1 E756del variant on severe malaria susceptibility." (PMID 34230590, 2022). "This multi-layered defense strategy—combining enhanced mechanical resistance with disruption of the intracellular environment—represents an elegant evolutionary adaptation to malaria pressure, explaining the high prevalence of these PIEZO1 variants in endemic regions." (PMID 41450567, 2025). "Polymorphisms and mutations in Piezo1 have been linked to malaria prevention." (PMID 38690080, 2024). "Thus, PIEZO1 activation in RBCs by Yoda1 or Jedi2 is anticipated to confer protection against malaria by two independent mechanisms, one involving a loss of discoid shape due to echinocytosis and an additional mechanism involving RBC dehydration." (PMID 37071200, 2023). "All together these data indicate that PIEZO1 GOF is protective against severe malaria, although the mechanisms implicated still remain unclear and controversial." (PMID 37071200, 2023). "A disease area to consider is malaria because gain‐of‐function mutation in PIEZO1 is associated with protection against malaria, and so this effect might be mimicked by a PIEZO1 agonist acting on wild‐type PIEZO1." (PMID 36457143, 2023). "The reason is that Piezo1 prevents plasmodium falciparum from entering red blood cells, and E756del has been shown to prevent even severe malaria." (PMID 38690080, 2024). "Recent work demonstrates that polymorphisms in the PIEZO1 gene causing a channel GOF, with a slower inactivation (i.e., increased channel opening), are associated with a protective effect against severe malaria both in humans and in a xerocytosis mouse model." (PMID 37071200, 2023).
malaria (continued). "We evaluated in vitro the effect of PIEZO1 activation by Yoda1 on human RBC infection by the malaria parasite Plasmodium falciparum." (PMID 37071200, 2023). "Our study focuses on the in vitro pharmacological activation of PIEZO1 in human RBCs and its impact on invasion, growth and development of the malaria parasite P. falciparum." (PMID 37071200, 2023). "Although the link between inherited PIEZO1 GOF variants and resistance against malaria is now well established, the mechanism(s) of protection still remain elusive and controversial." (PMID 37071200, 2023). "The chemically unrelated Jedi2 PIEZO1 activator similarly causes echinocytosis and RBC dehydration associated with resistance to malaria invasion." (PMID 37071200, 2023). "It is likely that a combination of effects involving RBC dehydration, decreased expression of the cytoadherence molecule PfEMP-1, and modulation of the immune system mediate the PIEZO1-dependent protection against severe malaria." (PMID 37071200, 2023). "Sickle cell trait, which may also affect RBC shape, associated with resistance to Plasmodium, the causative agent in malaria, prompting investigation of the relevance of DHS-associated PIEZO1 variants to malaria." (PMID 40628291, 2025). "Meanwhile, activating Piezo1 has been shown in vivo and in vitro to protect humans from malaria." (PMID 38690080, 2024). "Recently, it was confirmed that in children from Gabon, the PIEZO1 E756del variant is strongly associated with protection against severe malaria in heterozygotes, independent of the protection conferred by the sickle cell trait (HbS)." (PMID 37071200, 2023). "However, the PIEZO1-dependent mechanisms at play conferring the resistance to severe malaria remain debated." (PMID 37071200, 2023). "Thus, both PIEZO1 pharmacological activation (as well as PIEZO1 gain-of-function mutations) and SCD cause a change in the shape of RBCs and confer a significant protection against malaria, although apparently through distinct mechanisms." (PMID 37071200, 2023). "Previous works showed that human RBCs from African individuals carrying gain-of-function PIEZO1 allele (E756del) were dehydrated and could attenuate intracellular growth of P. falciparum strain in vitro, indicating that Piezo1 in RBCs had significant resistance against severe malaria." (PMID 38303078, 2024). "However, another report found no significant protection of the PIEZO1 E756del variant against severe malaria in a Ghanaian study." (PMID 37071200, 2023). "The chemically unrelated PIEZO1 activators Yoda1 and Jedi2, similarly inhibit P. falciparum parasitemia (although at different concentrations), suggesting a PIEZO1-dependent mechanism (Piezo1 orthologues are not present in the malaria parasite)." (PMID 37071200, 2023). "PIEZO1 E756del has also been shown to lead to iron overload by increasing RBC turnover through phagocytosis by macrophages, although whether or not this effect may be related to malaria protection is unknown." (PMID 37071200, 2023).
non-small cell lung carcinoma (12 papers, 2020 to 2025). A group of at least three distinct histological types of lung cancer, including non-small cell squamous cell carcinoma, adenocarcinoma, and large cell carcinoma. "Notably, a recent study also reported that Piezo1 deficiency accelerated the progression and cell migration of non-small cell lung cancer, suggesting that mechanical stimuli-mediated Piezo1 induction may also adopt an anti-cancer role." (PMID 35942515, 2022). "For example, in human non-small cell lung cancer, especially lung adenocarcinoma patients, high Piezo1 expression correlates with better overall survival, and knockdown of Piezo1 significantly promotes cancer cell migration in vitro and tumor growth in vivo." (PMID 38690080, 2024). "In lung cancer, similar to its homolog Piezo1, Piezo2 is negatively correlated with overall survival in non-small cell lung cancer patients." (PMID 37762011, 2023). "In non-small cell lung cancer cells, silencing of either Piezo1 or Piezo12 genes resulted in a notable increase in cell migration in vitro and tumor growth in vivo." (PMID 37305437, 2023). "Expression of Piezo1 in epithelial cells was also reported to influence the development of non-small cell lung cancer (NSCLC)." (PMID 35906615, 2022). "However, in contrast to all the other cancer types described, in non-small cell lung cancer patients, Piezo1 is expressed at low levels, and this low expression is linked to poor overall survival due to an increase in cell migration and tumor growth." (PMID 37762011, 2023). "In studies of non-small cell lung cancer (NSCLC), Piezo1 knockdown enhanced migration and tumor growth." (PMID 34831037, 2021). "Piezo1 mRNA levels are equally downregulated in small-cell lung carcinoma (SCLC) and in non-small-cell lung cancer (NSCLC)." (PMID 32635333, 2020).
pancreatitis (11 papers, 2018 to 2025). Inflammation of the pancreas. "Since Piezo1 is a rapidly inactivating channel, Piezo1 opening produces only transient elevation in [Ca2+]i that alone was insufficient to cause pancreatitis." (PMID 37781915, 2023). "We recently reported that pancreatic acinar cells express Piezo1 and that elevated pancreatic pressure can cause pancreatitis." (PMID 35451372, 2022). "In pancreatic acinar cells, the activation of Piezo1 by shear stress on pancreatitis acinar cells resulted in a transient elevation of Ca2+ that was insufficient to result in the mitochondrial dysfunction and necrosis associated with pancreatitis." (PMID 34795674, 2021). "Once Piezo1 was discovered in pancreatic acini, it seemed possible that excess mechanical stimulation could cause pancreatitis through a calcium-sensitive mechanism, implying that precise regulation of [Ca2+]i was necessary to prevent pancreatitis." (PMID 37781915, 2023). "In contrast, the administration of GsMTx4 or the genetic deletion of Piezo1 in acinar cells protected mice against pressure-induced pancreatitis." (PMID 38379701, 2024). "Pressure-induced pancreatitis was reduced in mice with either acinar cell–specific deletion of Piezo1 or global deletion of Trpv4." (PMID 37781915, 2023). "Other cation/calcium channels (e.g., Piezo) have been shown to have an effect on immune cells in a mechanosensitive manner and interestingly recent work demonstrates TRPV4 is required for Piezo1-induced pancreatitis." (PMID 32676078, 2020). "To determine if this effect is through Piezo1 activation, we induce pancreatitis by intrapancreatic duct instillation of the Piezo1 agonist Yoda1." (PMID 29712913, 2018). "These animals were then used to determine the role of Piezo1 in mediating pressure-induced pancreatitis by subjecting tamoxifen-treated Ptf1a-CreER;Piezo1fl/fl (Piezo1aci KO) and Piezo1fl/fl (WT) mice to intrapancreatic duct pressure." (PMID 29712913, 2018). "Blockade of Yoda1’s effects on acinar cells with GsMTx4 suggests that Piezo1 activation is the inciting event in the pancreatitis cascade." (PMID 29712913, 2018). "Our observation that Piezo1 activation directly damages acinar cells raises the possibility that elevated pressure within the pancreas contributes to the progression of pancreatitis through a Piezo1-mediated mechanism." (PMID 29712913, 2018). "Here the authors show that the mechanoreceptor Piezo1 is activated by pressure and its activation leads to calcium dependent pancreatic injury whereas its inhibition is protective against pancreatitis." (PMID 29712913, 2018). "Here we demonstrate that pancreatic acinar cells express the mechanoreceptor Piezo1 and application of pressure within the gland produces pancreatitis." (PMID 29712913, 2018). "Our observations with Yoda1 support this notion since activation of Piezo1 with Yoda1 produced pancreatitis in vivo." (PMID 29712913, 2018). "Infusion of the Piezo1 agonist Yoda1 through the pancreatic duct was shown to induce all parameters of pancreatitis in mice, including pancreatic edema, hemorrhage, necrosis and inflammatory cell infiltration, as well as elevated blood amylase and myeloperoxidase." (PMID 38379701, 2024). "An initial transient activation of Piezo1 by mechanical forces was shown to facilitate subsequent TRPV4 channel opening in pancreatic acinar cells with exaggeration of this mechanism leading to the pressure-induced pancreatitis." (PMID 38043795, 2023). "Importantly, mice with acinar cell–selective Piezo1 knockout were protected against pressure-induced pancreatitis." (PMID 37781915, 2023). "Finally, selective acinar cell-specific genetic deletion of Piezo1 protects mice against pressure-induced pancreatitis." (PMID 29712913, 2018). "Furthermore, blockade of Piezo1 channels and specific pancreatic acinar cell Piezo1 deletion protects mice from pancreatitis." (PMID 29712913, 2018).
pancreatitis (continued). "In contrast, Yoda1 did not cause pancreatitis in mice with genetic ablation of Piezo1 in acinar cells." (PMID 29712913, 2018). "Pancreatitis induced by pressure within the gland is prevented by a Piezo1 antagonist." (PMID 29712913, 2018). "Nevertheless, the finding that pharmacological or genetic deletion of Piezo1 in mice of slightly different backgrounds exhibited similar patterns of protection against pancreatitis reinforces the concept that Piezo1 mediates pressure-induced pancreatitis." (PMID 29712913, 2018). "However, sustained elevation in intracellular calcium is necessary for pancreatitis, and this study demonstrates that Piezo1 activation triggers the opening of the TRPV4 channel, which leads to sustained elevation in intracellular calcium and the development of pancreatitis." (PMID 38379701, 2024). "Thus, activation of Piezo1 in pancreatic acinar cells is a mechanism for pancreatitis and may explain why pancreatitis develops following pressure on the gland as in abdominal trauma, pancreatic duct obstruction, pancreatography, or pancreatic surgery." (PMID 29712913, 2018). "Moreover, our current findings suggest that strategies to block Piezo1 could be used to prevent pancreatitis when manipulation of the pancreas is anticipated as with pancreatic surgery or ERCP." (PMID 29712913, 2018). "Piezo1 blockade may prevent pancreatitis when manipulation of the gland is anticipated." (PMID 29712913, 2018). "Piezo1 and TRPV4 have been shown to work synergistically in several pathological states, such as osteoarthritis and pancreatitis." (PMID 34795674, 2021). "Moreover, Piezo1 and TRPV4 play a role in pressure-induced pancreatitis, which might act as a precursor lesion for PDAC." (PMID 40019468, 2025).
cardiomyopathy (10 papers, 2018 to 2025). A disease of the heart muscle or myocardium proper. "Together, we demonstrate that PIEZO1 GOF mutation contributes to cardiomyopathy by disrupting myocardial lipid metabolism." (PMID 41237237, 2025). "The unexplained cardiomyopathy observed in PIEZO1 GOF mutation carriers prompted us to investigate the etiology of PIEZO1-associated cardiomyopathy." (PMID 41237237, 2025). "Given the frequent observation of myocardial iron accumulation in these patients, it is clinically assumed that iron overload is the etiology underlying PIEZO1-related cardiomyopathy." (PMID 41237237, 2025). "Pathologically elevated PIEZO1 expression has been linked to myocardial infarction (MI) in animal models, leading us to hypothesize that PIEZO1 levels would also increase in cardiomyopathy patients." (PMID 40344385, 2025). "However, the relationship between PIEZO1 mutations and the development of cardiomyopathy remains unclear." (PMID 41237237, 2025). "By integrating evidence from humans and animal studies, we confirmed an important role for PIEZO1 GOF in the pathogenesis of cardiomyopathy." (PMID 41237237, 2025). "Our findings highlight that PIEZO1 GOF mutations alter cardiac lipid metabolism, providing the first evidence of the role of PIEZO1 in cardiomyopathy through lipid metabolic dysregulation." (PMID 41237237, 2025). "In this study, we confirmed that PIEZO1 contributes to cardiomyopathy through an iron-independent mechanism." (PMID 41237237, 2025). "Recent advances in understanding the role of PIEZO1 in iron overload and excitation-contraction coupling have raised critical questions regarding the etiology of PIEZO1-related cardiomyopathy." (PMID 41237237, 2025). "Mechanistic investigations revealed that Piezo1 GOF mutation increases calcium influx, contributing to cardiolipotoxicity and the development of cardiomyopathy through calcium signal–induced activation of the CaMKII-Foxo3 axis." (PMID 41237237, 2025). "This study challenges the current clinical focus on iron-related mechanisms in cardiomyopathy and supports PIEZO1 as a potential candidate for future genetic screening for cardiomyopathy." (PMID 41237237, 2025). "Here, we observed conformational changes that increased intracellular Ca2+ influx upon PIEZO1 GOF mutation and revealed that PIEZO1 GOF mutations promote lipid accumulation and cardiomyopathy." (PMID 41237237, 2025). "Our data revealed that Foxo3 overexpression significantly reduced lipid accumulation and alleviated cardiomyopathy in the presence of Piezo1 GOF." (PMID 41237237, 2025). "In summary, our study highlights the crucial role of PIEZO1 in cardiomyopathy therapy, showing that its targeted modulation can significantly improve treatment outcomes for MI." (PMID 40344385, 2025). "It has been reported that PIEZO1 converts the mechanical stretch of cardiomyocytes into Ca2+ and ROS signaling and affects cardiomyopathy progression." (PMID 38494915, 2024). "Either cardiac-specific knockout or overexpression of Piezo1 in mice results in defective Ca2+ and ROS signaling and the development of cardiomyopathy, demonstrating a homeostatic role of Piezo1." (PMID 33558521, 2021). "Given that both deletion and overexpression of Piezo1 can lead to heart dysfunction in mice, we wondered the pathological contribution of Piezo1 to cardiomyopathy." (PMID 33558521, 2021). "In this study, we propose that the pathogenesis of PIEZO1-related cardiomyopathy is multifactorial." (PMID 41237237, 2025). "Genome exon sequencing revealed a monoallelic variant of PIEZO1 (c.2005G > T, NM_001142864, p.D669Y) in the proband as a pathogenic gene for HX, with no known pathogenic or likely pathogenic cardiomyopathy loci detected." (PMID 41237237, 2025). "Therefore, physiological cardiac myocyte PIEZO1 seems to be protective against cardiomyopathy." (PMID 40721314, 2025).
cardiomyopathy (continued). "Indeed, an autonomic upregulation of Piezo1 in cardiomyocytes contributes to cardiomyopathy in both cellular and animal models, as well as in human patients, which might have altered mechanical stress conditions." (PMID 33558521, 2021). "Presumably, an upregulation of Piezo1 might initially serve as an adaptive response to meet the mechanical load of the heart under pathological or aging conditions, but eventually lead to cardiomyopathy due to the positive feedback mechanism on Ca2+ and ROS signaling." (PMID 33558521, 2021). "Our results indicate that PIEZO1 GOF contributes to cardiomyopathy partly independent of iron overload." (PMID 41237237, 2025). "Despite that the exact reason for the age-dependent phenotype remains unclear, we currently speculate that such a hypothesis might explain why only Piezo1-KO mice at 18-week old but not at 8-week old developed cardiomyopathy." (PMID 33558521, 2021).